DDX21 (DExD-box helicase 21)
Diseases named in the same sentence as DDX21 in open-access papers (continued):
Sharing a sentence is not in itself a finding about the gene and the disease.
acute myeloid leukemia (7 papers, 2022 to 2025). Acute myeloid leukemia (AML) is a group of neoplasms arising from precursor cells committed to the myeloid cell-line differentiation. "For example, the SE-driven m6A readers IGF2BP2/3 stabilise DDX21 mRNA to facilitate the progression of acute myeloid leukaemia, and the SE-regulated lncRNA LINC01089 induces alternative splicing of DIAPH3 through m6A modification to drive hepatocellular carcinoma progression." (PMID 41436435, 2025). "DDX21 has also been studied in other cancers, including neuroblastoma, acute myeloid leukemia (AML), and lymphoma." (PMID 39769343, 2024). "IGF2BP2 and IGF2BP3 augmented the stability of DDX21 mRNA in an m6A-dependent manner, followed by recruitment of transcription factor YBX1 by DDX21 on ULK1 gene promoter and elevated transcription of ULK1, which facilitates progression of acute myeloid leukemia." (PMID 39866844, 2025). "In acute myeloid leukemia (AML), DDX21 recruits YBX1 to cooperatively trigger ULK1 expression and promote AML progression." (PMID 40301349, 2025).
viral infection (7 papers, 2014 to 2024). "Therefore, DDX21 proteins with single, double, and triple mutations of these three Asp sites were generated, followed by transfection and virus infection." (PMID 34125604, 2021). "By exploring its functions and mechanisms in molecular biology, cancer, and viral infections, the potential of DDX21 as a therapeutic target becomes increasingly clear, underscoring its significance." (PMID 39769343, 2024). "In viral infections, DDX21 not only modulates viral replication but also plays a role in the host’s innate immune response, exerting both positive and negative effects." (PMID 39769343, 2024). "Investigating the context-dependent roles of DDX21 in various cancers and viral infections will provide deeper insights into its functional diversity." (PMID 39769343, 2024). "DDX21 can interact with other helicases to initiate innate immune reactions during viral infections." (PMID 39769343, 2024). "Current research is heavily focused on investigating DDX21’s role in viral infections, particularly its ability to inhibit viral expression during the early stages of infection." (PMID 39769343, 2024). "In this article, we discussed the regulatory role of DDX21 in RNA metabolism, cancer, and viral infections, summarizing its molecular functions in specific cancers and viral infections." (PMID 39769343, 2024). "Future research needs to further elucidate the specific regulatory mechanisms of DDX21 in different viral infections to better understand its role in innate immunity." (PMID 39769343, 2024). "In another study, caspase-3/6 cleavage of DDX21 at position D126 promotes its translocation from the nucleus to the cytoplasm during viral infection." (PMID 39769343, 2024). "Recent research has increasingly highlighted the importance of DDX21 in cancer and viral infections, revealing its potential as a biomarker and therapeutic target in these diseases." (PMID 39769343, 2024). "This review provides a thorough examination of the biological functions of DDX21, its involvement in cancer progression and viral infections, and its potential as both a biomarker and a therapeutic target." (PMID 39769343, 2024). "This section explores how DDX21 modulates the viral infection process, emphasizing its dual role in both antiviral defense and viral pathogenesis." (PMID 39769343, 2024). "Through this exploration, we found that DDX21 has emerged as a potential biomarker and therapeutic target for various cancers and viral infections, with significant implications for cancer prognosis and antiviral treatment strategies." (PMID 39769343, 2024). "Our data showed the obvious cleavage of DDX21 in response to virus infection and treatment with ligands." (PMID 34125604, 2021). "Our results showed that (i) the blockage of DDX21 cleavage inhibits DDX21 translocation and (ii) the most efficient translocation of cDDX21 occurs upon virus infection." (PMID 34125604, 2021). "Here, we report that virus infection and RNA/DNA ligands cleave DDX21 at D126 via the caspase-3/6 pathway." (PMID 34125604, 2021). "Recently, several reports indicated that DDX21 also plays a role in innate immunity and virus infection." (PMID 34125604, 2021). "An indirect immunofluorescent antibody test was performed with anti-DDX21 to localize DDX21 and determine its translocation during viral infection." (PMID 34578346, 2021). "Caspase-3/6 cleaves DDX21 at D126 and promotes its translocation from the nucleus to the cytoplasm in response to virus infection." (PMID 34125604, 2021). "Here, we demonstrated that DDX21 is cleaved at D126 after virus infection and RNA/DNA ligand treatment via the caspase-3/6 pathway, leading to the inhibition of immune responses." (PMID 34125604, 2021). "Here, we identified that DDX21 undergoes caspase-dependent cleavage after virus infection and treatment with RNA/DNA ligands, especially for RNA virus and ligands." (PMID 34125604, 2021).
viral infection (continued). "DDX21 was cleaved and translocated from the nucleus to the cytoplasm in response to virus infection." (PMID 34125604, 2021). "Collectively, these results clearly demonstrated that DDX21 was cleaved by virus infection and treatment with RNA/DNA ligands." (PMID 34125604, 2021). "The cleavage of DDX21 promotes its translocation from the nucleus to the cytoplasm in response to virus infection." (PMID 34125604, 2021). "Our studies are the first to highlight the role of S100A9 protein and DDX21-TRIF-S100A9-TLR4-MyD88 signaling network in modulating inflammation during virus infection." (PMID 24391503, 2014). "This review aims to provide a detailed analysis of DDX21, including its structural and functional features, its roles in cancer therapy and viral infection management, and its potential as a therapeutic target, with an emphasis on RNA metabolism, oncology, and host–pathogen interactions." (PMID 39769343, 2024). "In addition to its well-established role in cancer progression, DDX21 is crucial for the regulation of viral infections, owing to its RNA-binding and helicase activities." (PMID 39769343, 2024). "However, increasingly more evidence has shown that virus infection or treatment with stimulants, such as poly (I: C) and 3p-hpRNA, promote the translocation of DDX21 from the nucleus to the cytoplasm." (PMID 35336874, 2022). "Virus infection effectively triggered DDX21 translocation from the nucleolus to the cytoplasm." (PMID 34125604, 2021). "As expected, both RNA and DNA ligands cleaved DDX21, and a higher cleavage efficiency was observed upon treatment with RNA ligands than upon treatment with DNA ligands, which is in accordance with the results of virus infection." (PMID 34125604, 2021). "It should be noted that based on the molecular weight of DDX21, we proposed that the “cDDX21” that we observed with endogenous cleavage (∼73 kDa) was DDX21 127–784, while the relatively small cleaved DDX21 (∼14 kDa) was degraded upon virus infection." (PMID 34125604, 2021). "Cleavage of DDX21 by virus infection and treatment with RNA/DNA ligands." (PMID 34125604, 2021). "We found that DDX50 might be as a positive regulator of HTNV replication, indicating that DDX50 harbored opposite effects against DDX21 upon viral infection." (PMID 28676847, 2017). "Interestingly, the regulation of host DDX21 is dynamic during different stages of viral infection." (PMID 39769343, 2024). "However, how DDX21 precisely regulates antiviral innate immunity and whether DDX21 undergoes protein modification during virus infection remain unclear." (PMID 34125604, 2021). "The N protein of SARS-CoV-2 has been found to interact with several RNA helicases, including DDX1, DDX3, DDX5, DDX6, DDX21, and DDX10; among them, DDX1, DDX5, and DDX6 are essential for virus replication, while DDX21 and DDX10 restrict the viral infection." (PMID 38328580, 2023). "In addition, the overexpression of DDX21 increased IFN-β and IL-8 production in FMDV-infected cells to subvert the viral infection." (PMID 34578346, 2021). "As expected, WT, but not 1–125 and 127–784, DDX21 was cleaved upon virus infection." (PMID 34125604, 2021). "Most importantly, the cleavage of DDX21 inhibits innate immunity but does not affect virus infection, which leads us to speculate that the cleavage of DDX21 was driven by the host for a late counterregulatory effect to temper immune responses." (PMID 34125604, 2021).
melanoma (6 papers, 2020 to 2025). A malignant, usually aggressive tumor composed of atypical, neoplastic melanocytes. "In cancer, DDX21 associated with the progesterone receptor and modulated leflunomide-induced nucleotide stress in melanoma cells." (PMID 39866844, 2025). "DDX21 has been implicated in the development of various cancers, including breast, gastric, colorectal and melanoma cancers." (PMID 39690141, 2024). "A study reported that in zebrafish neurons and human melanoma cells, the pol I-binding RNA helicase, DDX21, was localized from the nucleolus to the nucleoplasm by DHODH inhibitors and increased its binding to mRNA." (PMID 36412986, 2022). "Leflunomide abrogates the effective transcription elongation of genes required for neural crest development and melanoma growth in vivo, and nucleotide depletion reduces the chromatin occupancy of the RNA helicase protein DDX21 in human A375 melanoma cells." (PMID 33971967, 2021). "To address if the zebrafish Prl3a-Ddx21 interaction is conserved in human cells, we generated A375 melanoma cells that stably express human PRL3 fused to HA." (PMID 32652076, 2020). "PRL3 restricts productive transcription of MITF endolysosomal target genes bound by DDX21 in the melanocyte stem cell lineage to prevent premature melanoblast expansion during regeneration and in melanoma." (PMID 32652076, 2020). "DDX21 acts as a sensor of nucleotide stress and contributes to melanoma development." (PMID 37072811, 2023). "To investigate whether genes regulated by PRL3 are targeted by DDX21, we compared a DDX21 chromatin immunoprecipitation sequencing (ChIP-seq) dataset from A375 melanoma cells to our PRL3-dependent 5′ enriched genes." (PMID 32652076, 2020). "In cells that express high endogenous PRL3 (C092 melanoma cells), we found that PRL3 and DDX21 co-localized as punctate clusters in the nucleoplasm." (PMID 32652076, 2020).
neuroblastoma (5 papers, 2021 to 2024). Neuroblastoma (NB) is the most common solid, extracranial childhood tumor. "In neuroblastoma, where the amplification of the MYCN oncogene is commonly associated with poor prognosis, N-MYC upregulates DDX21 transcription." (PMID 39769343, 2024). "In a study by Vina Putra on neuroblastoma, elevated levels of DDX21 were found to be correlated with high levels of N-Myc and CEP55 expression." (PMID 37988222, 2023). "In human neuroblastoma tissues, high levels of DDX21 expression correlate with high levels of N‐Myc expression and predict poor patient prognosis, independent of the current standard prognostic markers." (PMID 33497018, 2021). "We found that DDX21 promotes MYCN‐amplified neuroblastoma cell proliferation and clonogenic capacity, and high DDX21 gene expression correlates with poor patient prognosis." (PMID 33497018, 2021). "Knocking down DDX21 or CEP55 reduced neuroblastoma cell cytoskeleton stability and cell proliferation and all but abolished clonogenic capacity." (PMID 33497018, 2021). "Knocking down DDX21 or CEP55 significantly decreases neuroblastoma cell cytoskeletal stability and cell proliferation." (PMID 33497018, 2021). "In the current study, genome‐wide differential gene expression analysis identifies CEP55 as one of the few genes markedly downregulated after DDX21 knockdown in neuroblastoma cells." (PMID 33497018, 2021). "Genome‐wide differential gene expression studies identified centrosomal protein CEP55 as one of the genes most dramatically downregulated after DDX21 knockdown in MYCN‐amplified neuroblastoma cells." (PMID 33497018, 2021). "In human neuroblastoma tissues, a high level of DDX21 expression correlated with a high level of N‐Myc expression and with CEP55 expression, and independently predicted poor patient prognosis." (PMID 33497018, 2021). "In mouse models of MYCN‐amplified neuroblastoma, DDX21 knockdown initially induces tumor regression, suppresses tumor progression, and significantly improves the overall survival." (PMID 33497018, 2021). "Moreover, elevated DDX21 expression independently predicted poor prognosis in patients, and knocking out DDX21 led to regression of neuroblastoma tumors in mice and suppressed tumor progression." (PMID 37988222, 2023). "We therefore examined whether DDX21 or CEP55 plays key roles in microtubule stability in neuroblastoma cells." (PMID 33497018, 2021). "We then assessed whether DDX21 or CEP55 is required for neuroblastoma cell viability and/or proliferation." (PMID 33497018, 2021). "Importantly, DDX21 knockdown initially induced tumor regression in neuroblastoma‐bearing mice and suppressed tumor progression." (PMID 33497018, 2021). "Knocking down DDX21 suppressed tumor progression in neuroblastoma‐bearing mice." (PMID 33497018, 2021). "We next examined whether DDX21 increases the clonogenic capacity of neuroblastoma cells." (PMID 33497018, 2021). "We next examined whether DDX21 contributes to neuroblastoma tumor progression in vivo." (PMID 33497018, 2021). "For instance, DDX21 was reported to induce CEP55 expression, MYCN-amplified neuroblastoma cell proliferation, and tumorigenesis." (PMID 35371306, 2022). "N‐Myc upregulated DDX21 gene transcription, which subsequently upregulated CEP55 transcriptional elongation and resulted in increased neuroblastoma cell proliferation in vitro and tumor progression in mice." (PMID 33497018, 2021). "The results therefore indicate that DDX21 regulates CEP55 expression and promotes neuroblastoma progression in vivo." (PMID 33497018, 2021). "Our data demonstrate that DDX21 and CEP55 are potential therapeutic targets for MYCN‐amplified neuroblastoma." (PMID 33497018, 2021). "Taken together, these data indicate that DDX21 and CEP55 play important roles in maintaining neuroblastoma cell cytoskeletal stability and in driving cell proliferation." (PMID 33497018, 2021).
neuroblastoma (continued). "To further confirm the regulation of DDX21 expression by N‐Myc, we used doxycycline (DOX) withdrawal‐inducible N‐Myc overexpressing SHEP‐21N neuroblastoma cells." (PMID 33497018, 2021). "In human neuroblastoma tumor tissues, high CEP55 gene expression correlated with high DDX21 gene expression and independently predicts poor patient survival." (PMID 33497018, 2021). "In summary, the results indicate that DDX21 and CEP55 are essential for neuroblastoma cell proliferation and survival." (PMID 33497018, 2021). "Our data demonstrate that DDX21 and CEP55 are valid therapeutic targets for the treatment of MYCN‐amplified neuroblastoma." (PMID 33497018, 2021). "Taken together, our data show that DDX21 induces CEP55 expression, MYCN‐amplified neuroblastoma cell proliferation, and tumorigenesis, and that DDX21 and CEP55 are valid therapeutic targets for the treatment of MYCN‐amplified neuroblastoma." (PMID 33497018, 2021). "Here, we show that N‐Myc protein binds to the DDX21 gene promoter, leading to increased CEP55 expression, neuroblastoma cell cytoskeletal stability, and cell proliferation." (PMID 33497018, 2021). "In addition, high DDX21 expression correlated with high N‐Myc and centrosomal protein 55 (CEP55) expression and predicted poor patient prognosis in human neuroblastoma." (PMID 33497018, 2021). "In summary, these data demonstrate that N‐Myc regulates DDX21 expression and DDX21 regulates CEP55 expression in human neuroblastoma and that high DDX21 and high CEP55 expressions are independent prognostic markers of poor outcome in human neuroblastoma patients." (PMID 33497018, 2021).
lymphoma (4 papers, 2013 to 2024). A malignant (clonal) proliferation of B- lymphocytes or T- lymphocytes which involves the lymph nodes, bone marrow and/or extranodal sites.
colon cancer (3 papers, 2014 to 2022). "Only HSP90AB1, RIPK2, DDX21, UCHL5, GTPBP4, and PCID2 were significantly different in UC and COAD tissues, and they all showed overexpression in colon cancer tissues compared to UC tissues." (PMID 35372018, 2022).
hepatocellular carcinoma (3 papers, 2022 to 2025). A malignant tumor that arises from hepatocytes. "However, the role of DDX21 in the recurrence and prognosis of hepatocellular carcinoma (HCC) patients remains unknown." (PMID 39866844, 2025).
lung carcinoma (3 papers, 2021 to 2025). "In lung cancer, immunization with a Ddx21 mutant peptide (Ddx21^MT) generated durable anti-tumor immunity and increased central memory (T_CM) CD8+ T cells in mice, explaining the superior protection previously seen with an early-lesion–derived vaccine." (PMID 41293269, 2025). "In prophylactic settings, a Ddx21 mutant peptide generated durable anti-tumor immunity and central-memory T-cell expansion in murine lung-cancer vaccination, suggesting preventive or adjuvant opportunities when high-risk lesions are identifiable." (PMID 41293269, 2025). "Small molecule inhibitors of DDX21 could be developed with helicase targeting strategies similar to the discovery of DDX3 and DDX41 inhibitors, one of which (DDX3 inhibitor, RK‐33) is currently in a clinical trial in lung cancer patients." (PMID 33497018, 2021).
breast tumor (2 papers, 2014 to 2026). "Here, we demonstrate that the RNA helicase DDX21 facilitates breast tumor growth and metastasis by triggering HIF-mediated transcription elongation." (PMID 42311859, 2026). "Our results indicated that DDX21 was highly expressed in 25% of the 67 cases of breast tumor tissues, while normal breast tissue and benign tumors all exhibited very weak staining for DDX21." (PMID 25260534, 2014).
colorectal tumors (2 papers, 2020 to 2023). "CTD analysis revealed associations between the core genes (RRP9 and DDX21) and diseases such as proliferation, scar tissue, colorectal tumors, scleroderma, and inflammation." (PMID 37988222, 2023). "CTD analysis indicated that RRP9 and DDX21 are associated with proliferation, scar tissue, colorectal tumors, scleroderma, and inflammation." (PMID 37988222, 2023). "Our findings are compatible with previous reports of increased DDX21 expression in colorectal tumors at both the mRNA level and the protein levels." (PMID 33328538, 2020).
dengue virus infection (2 papers, 2020 to 2024). "Dengue virus infection caused the cytoplasmic redistribution of DDX21 to suppress viral replication." (PMID 38380105, 2024). "DDX21 redistributes from the nucleus to the cytoplasm for inducing innate immune responses during dengue virus infection." (PMID 38380105, 2024). "The relocalization of nuclear DDX21 to the cytoplasm during dengue virus infection contributes to interferon responses; this is consistent with previous reports of DDX21 involvement in innate immune sensing." (PMID 32033386, 2020).
gastric antral vascular ectasia (2 papers, 2020 to 2022). Dilatation of the vessels in the antrum of the stomach. "DDX21, also known as nucleolar RNA helicase 2, is an autoantigen with autoantibodies detected in patients suffering from connective tissue diseases and gastric antral vascular ectasia (watermelon stomach disease)." (PMID 36505822, 2022).